PTTG1 (PTTG1 regulator of sister chromatid separation, securin)
Diseases named in the same sentence as PTTG1 in open-access papers (continued):
Sharing a sentence is not in itself a finding about the gene and the disease.
tumor (continued). "In KIRC, genes like TOP2A, PTTG1, and others showed a negative link with tumor purity but a positive association with various immune cell types." (PMID 40390492, 2025). "The interaction between PTTG1 and nuclear factor kappa-light-chain-enhancer of B cells (NF-κB) signaling represents a critical axis in cancer development and progression across multiple tumor types." (PMID 40072059, 2025). "Furthermore, in vivo study using mouse models has demonstrated that PTTG1 promotes tumor growth and proliferation." (PMID 38465336, 2024). "Additionally, the protein expression levels of SLA, BTG2, DDIT4, TUBA4A, and PTTG1 in LUAD tumor tissues and normal tissues were investigated using the Human Protein Atlas (HPA) database." (PMID 38200058, 2024). "Importantly, a robust correlation has been established between elevated PTTG1 levels and tumor invasiveness, positioning PTTG1 as a pivotal marker gene closely tied to tumor metastasis." (PMID 39688352, 2024). "T cells are essential in tumor immune responses, and PTTG1 may serve as a predictive biomarker for immune checkpoint blockade (ICB) responses." (PMID 39388011, 2024). "Proliferation markers included in the signature, like Ki67 and PTTG1, have long been used as predictor for tumor recurrence or as invasiveness-related biomarkers in PitNET and other entities, although their value accurately predicting PitNET tumorigenesis has not been definitely confirmed." (PMID 39548496, 2024). "Additionally, PTTG1 knockdown impaired the invasive ability of in situ LLC tumor-bearing mice, promoting a shift in the balance of IR-induced immune response towards active immunity." (PMID 38200058, 2024). "This study indicates that in clinical practice, patients can undergo puncture to obtain a very small amount of tumor tissue and detect the expression of PTTG1, indicating whether OAd5 treatment can be prioritized over chemotherapy." (PMID 37243239, 2023). "Our study examined PTTG1 expression levels, tumor stage, and grade using TCGA data from UCSC Xena." (PMID 37243239, 2023). "In our study, we verified that LTB and PTTG1 were highly expressed in tumor tissues and PTPRC was highly expressed in normal tissues using clinical surgical resection samples, but further mechanistic experiments are needed to verify the specific functions of these model genes." (PMID 37671160, 2023). "Pituitary tumor-transforming gene 1 (PTTG1) is overexpressed in various types of tumors and functions as an oncogene; it could also be a potential target in tumor therapy." (PMID 37243239, 2023). "PTTG1 is a securin with well-known oncogenic activity in several tumor histotypes." (PMID 38069214, 2023). "PTTG1 is highly expressed in tumor tissues and has the highest HR value." (PMID 37671160, 2023). "We confirmed these data by performing spheroid-formation assays, supporting the hypothesis that PTTG1/ZEB1 collaboration is needed for PTTG1 to carry out its effect on tumor progression, specifically through EMT-promoting activity." (PMID 36230799, 2022). "Indeed, PTTG1 contributes to the metastatic process and tumor progression through the transactivation of many targets, such as matrix metalloproteinase 2 (MMP-2)." (PMID 36230799, 2022). "Multiple studies have reported these four transcriptional targets of PTTG1 in tumor tissue." (PMID 35768832, 2022). "However, the high expression of PTTG1 in tumor cells can inhibit senescence, which has also been confirmed by many studies." (PMID 36527013, 2022).
tumor (continued). "The pituitary tumour‐transforming gene (PTTG1) is the index mammalian securin." (PMID 35050550, 2022). "Surprisingly, as a global transcriptional factor, PTTG1 could, directly and indirectly, induce the expression of genes and promote tumor development." (PMID 35768832, 2022). "In this research, we found that PTTG1 exhibited strong associations with TME and we speculated that it may influence the anti-tumour immune due to various mechanisms." (PMID 35037540, 2022). "Moreover, in vivo tumor xenograft studies, in which FoxM1 expressing wild type or knockout cells for PTTG1 were implanted in the spleen of nude mice, revealed decreased liver metastasis in the absence of PTTG1." (PMID 35805898, 2022). "Thus, we detected the expression level of PTTG1 protein in pRCC from the FUSCC cohort by using immunohistochemical staining and we found elevated PTTG1 expression in tumour tissues, and higher expression of PTTG1 is significantly relevant to both OS and PFS." (PMID 35037540, 2022). "Elevated upregulation of PTTG1 activated by lncRNA PTTG3P promotes tumor growth and metastasis." (PMID 35907846, 2022). "Consequently, it would be a promising method to analyze the role of PTTG1 in tumor using the multi-omics approach." (PMID 35281830, 2022). "The expression level of PTTG1 is closely related to tumour formation, angiogenesis, and metastasis." (PMID 35037540, 2022). "Interestingly, they found that PTTG1 correlated with more advanced tumor size and grade and was an independent predictor of poorer patient survival." (PMID 35805898, 2022). "In addition, the nuclear expression of PTTG1 has been correlated to a more aggressive phenotype, and to tumor recurrence." (PMID 36230799, 2022). "More importantly, the pro-tumor role of PTTG1 was preliminarily investigated in BLCA cell lines." (PMID 35768832, 2022). "Indeed, PTTG1 contributes to the metastatic process and tumor progression by transactivation of matrix metalloproteinase-2 (MMP-2)." (PMID 33430117, 2021). "Furthermore, overexpression of PTTG1 has been reported to enhance cell proliferation, induce cellular transformation, and promote in vivo tumor formation." (PMID 33250768, 2020). "In addition to its role in promoting ESCC, we also discussed the possibility of PTTG1 advancing tumor progression." (PMID 33552118, 2020). "Although the target genes of PTTG1 in different tissue cells might partially overlap, they also have tumor specificity." (PMID 33552118, 2020). "It was shown that PTTG1 played an essential role in the biological function of tumor cells." (PMID 33552118, 2020). "The mRNA levels of PTTG1 are increased in higher tumor grade as compared to the lower tumor grade." (PMID 32272902, 2020). "PTTG1 expression in neoplastic cells on the tumor infiltration area and in the intertubular spaces may reflect this property important for tumor cells in invading surrounding tissues and inducing neoplastic angiogenesis." (PMID 31572301, 2019). "We can speculate that these 2 factors can play a substantial role in tumor cell processes: while PTTG1 is involved in the cell cycle, Ki-67 is a marker of active cell proliferation, altered in numerous neoplasms and associated with the prognosis." (PMID 30911297, 2019). "PTTG1 in fact is known to play an important role in tumor infiltration and neoplastic angiogenesis." (PMID 31572301, 2019). "The overexpression of PTTG1 in human HCC tissues suggests that PTTG1 may have a tumor‐promoting function in hepatocarcinogenesis." (PMID 31385458, 2019). "However, overexpression of PTTG1 was positively associated with more advanced tumor size, tumor grade, and TNM stage (P < .01), which is consistent with the role of PTTG1 on tumor proliferation." (PMID 31385458, 2019). "The functional blocking of PTTG1 may induce suppression of tumor growth and metastasis development, by the down-regulation of MMP-2 expression." (PMID 31572301, 2019).
tumor (continued). "Moreover, the level of PTTG3P was positively correlated with PTTG1 mRNA in 46 HCC tumor tissues (R = 0.543, P < 0.05)." (PMID 29803224, 2018). "Higher levels of PTTG1 were observed in HCC tumor tissues than non-tumor tissues." (PMID 29803224, 2018). "Modulation of the tumor growth and metastasis effect through inhibiting PTTG1 up-regulation and PI3K/AKT activation mediated by PTTG3P suppression might be used as a potential target for HCC prevention and therapy." (PMID 29803224, 2018). "Our findings suggest that PTTG3P, a valuable marker of HCC prognosis, promotes tumor growth and metastasis via up-regulating PTTG1 and activating PI3K/AKT signaling in HCC and might represent a potential target for gene-based therapy." (PMID 29803224, 2018). "MiR-122 negatively regulates the expression of a tumor promoter, N-myc downstream-regulated gene 3 (NDRG3), or pituitary tumor-transforming gene 1 (PTTG1) binding factor (PBF) whose upregulation, because of the loss of miR-122 expression, leads to the cell growth and invasion of the HCC tumor." (PMID 29673190, 2018). "We also isolated the total protein of tumor, western blot assay suggested epithelial marker E-cadherin level was significantly increased, mesenchymal marker Vimentin was significantly reduced, confirming PTTG1 regulated EMT and metastasis." (PMID 27893422, 2017). "There was a significant correlation between high PTTG1 expression and TNM stage, tumor size, invasion and metastasis of BC, suggesting PTTG1 might be a potential biomarker for BC progression." (PMID 27893422, 2017). "However, more studies are needed to further understand the precise mechanisms of the FoxM1 and PTTG1 involved in different cellular contexts and tumor types, and in response to different types of damage." (PMID 26264222, 2015). "Notably, Pttg1 knockdown significantly reduced MM tumour development in vivo, with an 83.2 % reduction in tumour burden at 4 weeks (p < 0.0001, two-way ANOVA)." (PMID 26445238, 2015). "Tumour burden was decreased by 83 % in the Pttg1 knockdown group compared with the control group at 4 weeks (p < 0.0001, two-way ANOVA with Sidak’s post-test), suggesting that high basal expression of Pttg1 in 5TGM1 cells is important for in vivo tumour growth." (PMID 26445238, 2015). "To determine if SP17/AKAP4/PTTG1 could trigger a tumor-specific cytotoxic response, we used CTA-loaded DCs to generate CTLs." (PMID 25739119, 2015). "The overexpression of PTTG1 induced cell transformation in vitro and tumor formation in nude mice." (PMID 23977008, 2013). "In conclusion, we demonstrated that the overexpression of PTTG1 could be repressed by KLF6 tumor suppressor through the activation of PKC/ERK signaling in myeloid cell differentiation." (PMID 23977008, 2013). "During our recent investigations to understand the mechanisms by which PTTG1 is involved in tumor angiogenesis and metastasis, we performed transient and stable transfections of HEK293 cells with PTTG1 cDNA and studied the expression and secretion of matrix metalloproteinase (MMP)-2." (PMID 19014669, 2008). "Moreover, increased PTTG1 expression levels and early tumor recurrence has been found in different cancer series." (PMID 18426563, 2008). "Blocking or down regulation of PTTG1 in tumors may result in suppression of tumor growth and metastasis through the related down regulation of MMP-2 expression and activity." (PMID 19014669, 2008). "In addition, to test the presence of a putative epigenetic control over PTTG1 expression we performed PTTG1 expression analysis in three tumor cell lines with different basal expression levels." (PMID 18426563, 2008). "In conclusion, the functions of PTTG-1 are complex and antithetic and might differ from tumor cell to tumor cell." (PMID 16426442, 2006).
tumor (continued). "As a result, the staining intensity of PTTG-1 expression (p = 0.047), tumor stage (p = 0,051), performance status (p = 0.015), LDH level (p = 0.001) and hemoglobin level (p= 0.011) were identified as independent prognostic parameters by the Cox regression modell." (PMID 16426442, 2006). "Furthermore our data suggest that overexpression of PTTG1 in these cells results in a greater propensity for tumor development, a shortened latency period and an enhanced growth rate compared with pcDNA3.1-transfected control HEK293 cells." (PMID 15649325, 2005). "Recent studies have indicated that elevated expression of PTTG1 in some tumors may serve as a prognostic marker for tumor invasiveness and metastasis." (PMID 15649325, 2005). "Moreover, ASPH and PTTG1 may themselves play regulatory roles in drug response pathways, thereby influencing tumor cell sensitivity to specific treatments." (PMID 41312363, 2025). "Therefore, considering the crucial oncogenic role of PTTG1 in tumor progression, this study will further investigate the role of PTTG1 in NB, aiming to explore whether PTTG1 inhibits NB cell proliferation and growth by regulating autophagy." (PMID 41264123, 2025). "Interestingly, a cross-species comparative genomic analysis identified PTTG1 as one of 16 evolutionarily conserved genes crucial for tumor progression, with functional network analysis revealing its role in cell cycle regulation, DNA repair, and mitotic processes." (PMID 40072059, 2025). "This may represent a specific role of PTTG1 in the tumor microenvironment." (PMID 39144144, 2024). "In addition, PTTG1 could also be a potential target in tumor therapy for various types of cancer, such as melanoma, breast cancer, and ovarian cancer." (PMID 35281830, 2022). "Thus, PTTG1 could be potential biomarker for both prognosis and outcomes of tumor treatment and it could also be a promising target in tumor therapy." (PMID 35281830, 2022). "However, the potential role of PTTG1 in tumor formation and its prognostic function in human pan-cancer is still unknown." (PMID 35281830, 2022). "Hence, the relation and potential mechanism between PTTG1 and human pan-cancer could be obtained, which would also provide a novel approach for tumor treatment." (PMID 35281830, 2022). "This might reveal a potential mechanism between PTTG1 and tumor formation." (PMID 35281830, 2022). "All these results implied that PTTG1 might play an important role in tumor development." (PMID 36060253, 2022). "Overexpression of PTTG1 may lead to tumor formation and poor prognosis in various tumors." (PMID 35281830, 2022). "Additionally, PTTG1 may correlate with the BLCA tumor microenvironment and exert transcriptional activity by targeting CHEK2, OCIAD2, UBE2L3, and ZNF367 in BLCA tissue." (PMID 35768832, 2022). "However, the precise role of PTTG1 is not completely elucidated: it is probably cell line dependent and it is implicated in the physiological regulation of the cell cycle even in tumor cells." (PMID 30911297, 2019). "The involvement of PTTG1 in tumor growth and metastasis is further highlighted by several studies showing that in cancer cell lines of various histological derivation ectopic expression of PTTG1 enhanced proliferation and/or invasiveness, whereas PTTG1 silencing produced opposite results." (PMID 29371923, 2017). "Differential expression levels of PTTG1 and BATF between HCC and adjacent non-tumor tissues were further validated by immunohistochemistry (IHC) in 25 patient tissue samples." (PMID 40315269, 2025). "PTTG1 and VASP knockdown noticeably reduced the metastatic cell adhesion of tumor cells to the lungs after tail vein injection by treatment with siRNA‐PTTG1 or siRNA‐VASP, compared with the control." (PMID 39792809, 2025).
tumor (continued). "Our examinations showed a significant overexpression of five genes (CCNB1, CCNB2, PTTG1, RACGAP1, and UBE2C) in the tumor samples." (PMID 41009526, 2025). "These mouse models indicate that the depletion of PTTG1 and VASP represses metastatic tumor cell adhesion of OSCC in vivo." (PMID 39792809, 2025). "For instance, in the comparison between PCa tumor and normal samples, DiCE identified 61 cancer fitness genes, including MYC, CCNA2, PLK1, PTTG1, EPCAM, and MTOR, that were overlooked by typical DEA but are well-documented contributors to PCa progression." (PMID 40626556, 2025). "A heatmap of the 11 mRNA expression levels of the tumor samples displayed that the seven genes, including CCNB1, CCNB2, CHEK1, FEN1, PTTG1, RACGAP1, and UBE2C, had higher expression levels in the tumor tissue." (PMID 41009526, 2025). "PTTG1 modulates c-MYC expression and interacts with NF-κB signaling to support tumor cell proliferation and protect against apoptosis." (PMID 40072059, 2025). "As for the tumor-promoting mechanism, PTTG3P overexpression upregulates pituitary tumor-transforming 1 (PTTG1), activating the PI3K/AKT pathway and enhancing HCC growth, cell cycle progression, EMT, and metastasis in HCC." (PMID 39161590, 2024). "Cluster T00 highly expressed several known aggressive tumor markers (such as PTTG1, TOP2A) in comparison with other tumor epithelial clusters due to the higher proportion of cells in proliferation status." (PMID 38167466, 2024). "We then explored the crucial biomarkers of MRS1-tumor cells, finding that S100A7, S100A8, and PTTG1 were up-regulated in the MRS1 phenotype both in bulk data (TCGA-BLCA and GSE13057) and single-cell data." (PMID 37543645, 2023). "BAIAP2L2, pituitary tumour-transforming gene 1 (PTTG1) and complement factor H-related 3 (CFHR3) have also been reported to be overexpressed in many types of human cancer and to promote tumour cell angiogenesis, migration and invasion." (PMID 36217206, 2022). "Nevertheless, although not reaching significance, there was a trend of reduced expression of PLK1, KIF11, PTTG1 and TTK (the latter otherwise induced by DEXA in U25MG cells in DEXA treated tumours." (PMID 33478100, 2021). "The authors firstly demonstrated that PTTG1 marks some specific OCT4- and KLF4-positive tumor cells, mainly localized at the periphery of the neoplasm." (PMID 34209730, 2021). "In analysis of multiple tumor areas, prognostic value was observed for cytoplasmic BUB3, CCNB1, and PTTG1." (PMID 31801961, 2020). "One study using RT-PCR of 48 cases of ESCC and its matched samples revealed that PTTG1 expression was upregulated in ESCC, and the average expression level in tumor tissue was 2.19 times than that of normal tissue (0.105 vs. 0.048)." (PMID 33552118, 2020). "Positive scores in ≥1 tumor area were observed for 94 (38%) patients for CCNB1 and 103 (42%) patients for PTTG1." (PMID 31801961, 2020). "It was found that CSCs specifically expressed BIRC5, PTTG1, CENPF and CDKN3 genes and presented a scattering distribution in the bulk tumor tissues, which further verified the relatively rare characteristics of CSCs." (PMID 33162821, 2020). "PTTG1 marks some specific OCT4- and KLF4-positive tumor cells, mainly localized at the periphery of the neoplasm." (PMID 31572301, 2019). "We revealed that PTTG1 was frequently up-regulated and positively correlated with PTTG3P in 46 HCC tumor tissues." (PMID 29803224, 2018). "Even for the therapy-naïve study cohort, differential gene expression was a significant prognosticator within tumor sets defined by their WHO grades (WHO°I: AURKB, COX10, ECT2, UBE2C; WHO°II: LEPR, MN1; WHO°III: PTTG1, UBE2C)." (PMID 26894859, 2016).